MIR4782 (microRNA 4782)
Synonyms: hsa-mir-4782
Gene: MicroRNA gene on chromosome 2 (113,721,290 to 113,721,368, reverse strand). Ensembl gene ENSG00000265429.
Homologues: Orthologues: chimpanzee MIR4782 (100% identical).